BAZ2B (bromodomain adjacent to zinc finger domain 2B)
Description:
Regulatory subunit of the ATP-dependent BRF-1 and BRF-5 ISWI chromatin remodeling complexes, which form ordered nucleosome arrays on chromatin and facilitate access to DNA during DNA-templated processes such as DNA replication, transcription, and repair. Both complexes regulate the spacing of nucleosomes along the chromatin and have the ability to slide mononucleosomes to the center of a DNA template. The BRF-1 ISWI chromatin remodeling complex has a lower ATP hydrolysis rate than the BRF-5 ISWI chromatin remodeling complex. Chromatin reader protein, which may play a role in transcriptional regulation via interaction with ISWI (By similarity). Involved in positively modulating the rate of age-related behavioral deterioration (By similarity). Represses the expression of mitochondrial function-related genes, perhaps by occupying their promoter regions, working in concert with histone methyltransferase EHMT1 (By similarity).
Synonyms: WALp4
Tractability: Small molecule: a structure with a bound ligand is known; a high-quality ligand is known. PROTAC: UniProt records ubiquitination sites on it; ubiquitination databases record sites on it; a small molecule that binds it is known.
Target class: Epigenetic regulator; Bromodomain; Reader
Chemical probes: BAZ2-ICR (high quality), GSK2801 (high quality)
Gene: Protein-coding gene on chromosome 2 (159,315,312 to 159,617,282, reverse strand). Ensembl gene ENSG00000123636.
Subcellular location: Nucleus
Subcellular location (Human Protein Atlas): Nucleoplasm; Cytosol
Gene Ontology:
Molecular function: protein binding; DNA binding
Biological process: chromatin remodeling; regulation of transcription by RNA polymerase II
Cellular component: nucleus; chromatin
Genetic constraint (gnomAD): Loss-of-function variants: 71 observed, 224 expected, observed/expected ratio (o/e) 0.32, 90% interval 0.26 to 0.39. The upper end of that interval is the gene's LOEUF score, 0.39, which puts it in group 1 of 6, group 1 being the genes least tolerant of losing a copy. Missense variants: 2,194 observed, 2,482.2 expected, observed/expected ratio (o/e) 0.88, 90% interval 0.85 to 0.92. Synonymous variants: 810 observed, 854.64 expected, observed/expected ratio (o/e) 0.95, 90% interval 0.89 to 1.
Gene-disease validity (ClinGen):
ClinGen rates the evidence that BAZ2B causes each of these diseases.
complex neurodevelopmental disorder (autosomal dominant): Limited. A disorder that involves more than one phenotype associated with the central nervous system, including but not limited to intellectual disability, autism, and seizures (epilepsy).
Homologues: Orthologues: chimpanzee BAZ2B (99% identical), macaque BAZ2B (99% identical), dog BAZ2B (96% identical), pig BAZ2B (95% identical), rabbit BAZ2B (95% identical), guinea pig BAZ2B (94% identical), rat Baz2b (87% identical), mouse Baz2b (84% identical), tropical clawed frog baz2b (72% identical), zebrafish baz2ba (44% identical), Caenorhabditis elegans bet-1 (9% identical). Paralogues in human: BAZ2A (29% identical), BAZ1A (15% identical), BPTF (14% identical), BAZ1B (13% identical), BRD4 (7% identical), KAT2B (6% identical), CECR2 (6% identical), KAT2A (6% identical), BRD2 (5% identical), BRD3 (5% identical), BRDT (5% identical).
Diseases named in the same sentence as BAZ2B in open-access papers:
BAZ2B is named in the same sentence as 28 diseases in open-access papers, as found by Europe PMC text mining. Sharing a sentence is not in itself a finding about the gene and the disease. The quoted sentences say what the papers report.
asthma (3 papers, 2022 to 2025). "Knockdown of either lnc-BAZ2B or BAZ2B reduced inflammation in a cockroach allergen-induced asthma model, suggesting therapeutic potential." (PMID 40722500, 2025). "First, some lncRNAs such as MIR155HG, lnc-BAZ2B, and LARRPM studied in asthma, COPD, and lung cancer studies are based on a small sample size at present." (PMID 36685535, 2022). "Lnc-BAZ2B could promote the mRNA stability of BAZ2B and the transcription of IRF4, thereby promoting the activation of M2 macrophages in asthma." (PMID 38750059, 2024).
Intellectual disability (3 papers, 2021 to 2025). "Mutations in BAZ2B have recently been associated with neurodevelopmental disorders, including developmental delay, autism spectrum disorder and intellectual disability." (PMID 34032215, 2021). "BAZ2B haploinsufficiency was identified in patients with intellectual disability and autism." (PMID 40725218, 2025).
Alpha-thalassemia (1 paper, 2021). Alpha-thalassemia is an inherited hemoglobinopathy characterized by impaired synthesis of alpha-globin chains leading to a variable clinical picture depending on the number of affected alleles. "BAZ2B (Bromo-domain Adjacent to Zinc finger domain 2B), which binds to acetylated histone H3 lysine 14 (H3K14Ac) and the chromatin remodeler ATRX (Alpha Thalassemia/mental Retardation syndrome X) also correlate with elevated R/G ratios." (PMID 34174884, 2021).
childhood asthma (1 paper, 2022). "Lnc-BAZ2B promoted M2 macrophage activation and was significantly upregulated in childhood asthma, whereas LncRNA PTPRE-AS1 was downregulated in macrophage polarization which mediated type II inflammation." (PMID 35656293, 2022). "Moreover, lnc-BAZ2B also played a crucial role in exacerbating the progression of childhood asthma." (PMID 35656293, 2022).
COVID-19 (1 paper, 2024). A disease caused by infection with severe acute respiratory syndrome coronavirus 2. "A gene-based association test revealed a significant association in BAZ2B and in previously known COVID-19 risk loci: LZTFL1, XCR1, FYCO1, CCR9, and IFNAR2." (PMID 39361370, 2024). "Located within the BAZ2B gene, the sentinel variant rs13003835 is an intronic variant associated with an increased risk of COVID-19 hospitalization (odds ratio [OR]=1.20, 95% confidence interval [CI] = 1.12–1.27, p=3.66 × 10–8)." (PMID 39361370, 2024). "Genome-wide significant associations with COVID-19 hospitalizations were found on chromosome 2 (within BAZ2B), chromosome 3 (within LZTFL1), chromosome 6 (within FOXP4), and chromosome 11 (within DDIAS)." (PMID 39361370, 2024). "Here, we present the findings of a GWAS meta-analysis in admixed Latin American (AMR) populations, comprising individuals from the SCOURGE Latin American cohort and the HGI studies, which allowed us to identify two novel severe COVID-19 loci, BAZ2B and DDIAS." (PMID 39361370, 2024).
dementia (1 paper, 2023). Loss of intellectual abilities interfering with an individual's social and occupational functions. "However, only six of these genes emerged to be associated with AD in a certain way: HMGB1, which is related AD dementia according to ‘Disease Ontology’; KANSL1; BAZ2B; EHMT1; SIRT1; and CTBP1, which are associated with AD according to the literature data." (PMID 37175659, 2023).
leukemia (1 paper, 2018). A malignant (clonal) hematologic disorder, involving hematopoietic stem cells and characterized by the presence of primitive or atypical myeloid or lymphoid cells in the bone marrow and the blood. "The following sections summarize the eight top-ranked genes in some of the major drug classes (FLT3, CASP8AP2, L2HGDH, MNT, BAZ2B, MZF1, BEX2, and SMARCA4) that are highly likely to have notable biological significance in leukemia." (PMID 29298978, 2018).
Rett syndrome (1 paper, 2023). A severe neurodevelopmental disorder affecting the central nervous system.
cancer (5 papers, 2022 to 2024). A tumor composed of atypical neoplastic, often pleomorphic cells that invade other tissues. "Overall, the results indicate that the mutations identified in cancer patients have different effects on the function of the Baz2B bromodomain." (PMID 38000389, 2024). "Baz2B also has been described as a master regulator in the reprogramming of human haematopoietic progenitors and has been associated with viral infections, neurodevelopment, autism spectrum disorders, cancer, and unhealthy ageing." (PMID 38000389, 2024). "Furthermore, we examine the impact of cancer-associated point mutations in the Baz2B BRD, which destabilize the bromodomain, induce conformational changes, and lead to the loss or even a switch in acetylated H3 peptide binding affinity." (PMID 38000389, 2024). "Notably, several point mutations in the Baz2B bromodomain have been identified in human cancers." (PMID 38000389, 2024). "To gain deeper insights into the functional impact of cancer-associated mutations in the Baz2B bromodomain, we introduced single-point mutations in the BRD of Baz2B." (PMID 38000389, 2024). "The results demonstrated a reduced colony-forming capacity of the Baz2B-KO cells compared to the control cell line, suggesting that Baz2B plays a role in cancer cell proliferation in the Hap1 cell line." (PMID 38000389, 2024). "Altogether, these results indicate that Baz2B-KO cells exhibit alterations in the transcriptional landscape during cancer proliferation, while the global chromatin organisation remains similar to that of the parental Hap1 control cell line." (PMID 38000389, 2024). "In our report, we observed that BAZ2B correlates negatively with cancer stemness in distinct types of solid tumors, although it requires further study to determine the molecular mechanism of BAZ2B involvement in cancer de-differentiation." (PMID 36674511, 2023). "The expression of most BrD members significantly negatively correlated with cancer stemness across many TCGA tumor types, although only for KAT2B, KMT2A, SMARCA2, BAZ2B, SP100 and SP140, the association was highly consistent (regardless of the tumor type)." (PMID 35049055, 2022). "The more novel findings in this study were in genes (ARID5B, BAZ2B, RABGAP1, SFRP2, and WBP1L) that are associated with cancer risk and cellular differentiation." (PMID 36685876, 2022). "However, the role of BAZ2B in regulating cancer development and progression remains elusive." (PMID 36674511, 2023). "Non-synonymous single nucleotide polymorphisms mapping to the Baz2B bromodomain, obtained from the COSMIC and ICGC data portals, were present in various cancer patients, and these cancer patients acquired no more than 500 other mutations." (PMID 38000389, 2024). "Therefore, we focused our attention on three genes coding for bromodomain-containing proteins (BAZ2A, BAZ2B, and BRD9) that were all expressed in paclitaxel-resistant SW1736 and 8505C cancer cell lines." (PMID 36983070, 2023). "Five of these genes (ARID5B, BAZ2B, RABGAP1, SFRP2, WBP1L) are associated with cancer risk and cellular differentiation and have not been previously identified in MS studies." (PMID 36685876, 2022).
neoplastic diseases (2 papers, 2022). "ARID5B, BAZ2B, RABGAP1, SFRP2, and WBP1L have not been previously associated with MS risk, and all are associated with neoplastic diseases and cellular proliferation." (PMID 36685876, 2022).
infection (1 paper, 2020). The state of being infected such as from the introduction of a foreign agent such as serum, vaccine, antigenic substance or organism. "A 40–50% reduction of BAZ2B mRNA levels translated into a >50% inhibition of HDV replication at day 8 post infection." (PMID 31964889, 2020).
BAZ2B also shares sentences with these, for which no sentence is quoted: autism spectrum disorder (2 papers); Alzheimer disease (1); anaplastic thyroid carcinoma (1); autism (1); B-cell acute lymphoblastic leukemia (1); bladder cancer (1); colorectal cancer (1); developmental delay (1); lung carcinoma (1); lung squamous cell carcinoma (1); melanoma (1); mild cognitive impairment (1); neurodevelopmental disorder (1); neurological diseases (1); prostate carcinoma (1); schizophrenia (1); thyroid tumor (1).